TRIM13 (tripartite motif containing 13)
Description:
Endoplasmic reticulum (ER) membrane anchored E3 ligase involved in the retrotranslocation and turnover of membrane and secretory proteins from the ER through a set of processes named ER-associated degradation (ERAD). This process acts on misfolded proteins as well as in the regulated degradation of correctly folded proteins. Regulates ER stress-induced autophagy, and may act as a tumor suppressor. Also plays a role in innate immune response by stimulating NF-kappa-B activity in the TLR2 signaling pathway. Ubiquitinates TRAF6 via the 'Lys-29'-linked polyubiquitination chain resulting in NF-kappa-B activation. Participates as well in T-cell receptor-mediated NF-kappa-B activation. In the presence of TNF, modulates the IKK complex by regulating IKBKG/NEMO ubiquitination leading to the repression of NF-kappa-B.
Synonyms: LEU5; RFP2; RNF77; DLEU5; CAR
Tractability: Antibody: UniProt predicts a signal peptide or a membrane-spanning region. PROTAC: UniProt records ubiquitination sites on it; ubiquitination databases record sites on it; its protein half-life has been measured.
Gene: Protein-coding gene on chromosome 13 (49,995,888 to 50,020,481, forward strand). Ensembl gene ENSG00000204977.
Subcellular location: Endoplasmic reticulum membrane
Pathways (Reactome):
Metabolism of proteins: ER Quality Control Compartment (ERQC)
Gene Ontology:
Molecular function: protein binding; transcription coactivator activity; ubiquitin-like protein ligase activity; ubiquitin-protein transferase activity; ubiquitin protein ligase activity; zinc ion binding
Biological process: antiviral innate immune response; ERAD pathway; positive regulation of canonical NF-kappaB signal transduction; positive regulation of macroautophagy; proteasome-mediated ubiquitin-dependent protein catabolic process; protein autoubiquitination; suppression of viral release by host; endoplasmic reticulum mannose trimming; innate immune response; positive regulation of DNA-templated transcription; protein ubiquitination
Cellular component: endoplasmic reticulum membrane; perinuclear endoplasmic reticulum; cytoplasm; endoplasmic reticulum quality control compartment
Genetic constraint (gnomAD): Loss-of-function variants: 15 observed, 28.27 expected, observed/expected ratio (o/e) 0.53, 90% interval 0.35 to 0.82. The upper end of that interval is the gene's LOEUF score, 0.82, which puts it in group 3 of 6, group 1 being the genes least tolerant of losing a copy. Missense variants: 402 observed, 497.59 expected, observed/expected ratio (o/e) 0.81, 90% interval 0.74 to 0.88. Synonymous variants: 193 observed, 182.86 expected, observed/expected ratio (o/e) 1.06, 90% interval 0.94 to 1.19.
Homologues: Orthologues: chimpanzee TRIM13 (99% identical), macaque TRIM13 (97% identical), pig TRIM13 (93% identical), dog TRIM13 (92% identical), guinea pig TRIM13 (92% identical), rabbit TRIM13 (92% identical), mouse Trim13 (89% identical), rat Trim13 (87% identical), tropical clawed frog trim13 (59% identical), zebrafish trim13 (48% identical). Paralogues in human: MID1 (22% identical), MID2 (21% identical), TRIM27 (18% identical), TRIM39 (18% identical), TRIM4 (18% identical), TRIM41 (18% identical), TRIM5 (18% identical), TRIM60 (18% identical), TRIM61 (18% identical), TRIM10 (18% identical), TRIM11 (18% identical), TRIM43B (18% identical), and 68 more.